SETD5 (SET domain containing 5)
Diseases named in the same sentence as SETD5 in open-access papers (continued):
Sharing a sentence is not in itself a finding about the gene and the disease.
ciliopathy (1 paper, 2019). A genetic disorder of the cellular cilia or the cilia anchoring structures, the basal bodies, or of ciliary function. "The fourth patient, with an Alu insertion in SETD5, has clinical features (polydactyly and truncal obesity) more suggestive of a ciliopathy." (PMID 31604926, 2019).
clear cell renal cell carcinoma (1 paper, 2022). "MPM has similarities to clear cell renal cell carcinoma (ccRCC), as both harbour frequent loss of function mutations in SETD2, SETD5 and BAP1, and we confirm in this study PBRM1." (PMID 35637530, 2022).
colon adenocarcinoma (1 paper, 2023). "SETD5 expression in colon adenocarcinoma was linked to the distant metastasis (p = 0.027) and radiotherapy (p = 0.023) of the patients." (PMID 37963940, 2023). "SETD5 expression was moderately correlated with CD133 expression in colon adenocarcinoma (p < 0.009)." (PMID 37963940, 2023). "Moreover, OS and DFS analyses revealed that SETD5 expression was significantly associated with poor OS (p = 0.005) and DFS (p = 0.001) in patients with colon adenocarcinoma." (PMID 37963940, 2023). "To determine whether SETD5 plays a role in CSC function, we investigated the association between SETD5 and the CSC markers CD133 and CD44 in colon adenocarcinoma." (PMID 37963940, 2023).
erythroleukemia (1 paper, 2022). Acute erythroid leukemia characterised by the presence of at least 50% erythroid precursors and at least 20% myeloblasts in the bone marrow. "To explore the potential partners of SETD5, we performed co-immunoprecipitation (Co-IP) assay coupled with quantitative mass spectrometry (MS) using SETD5-FLAG stably expressed Hela or MEL (a murine erythroleukemia cell) cell lines." (PMID 34853439, 2022).
hypopituitarism (1 paper, 2024). A condition of diminution or cessation of secretion of one or more hormones from the anterior pituitary gland. "It will be intriguing to examine the effects of Setd5 deficiency on pituitary stem cell differentiation and gene expression, providing insight into the mechanism of hypopituitarism in some patients." (PMID 38822427, 2024).
inflammatory bowel disease (1 paper, 2025). A spectrum of small and large bowel inflammatory diseases of unknown etiology. "Mutations in SETD5 and KDM3B connect OCD with Inflammatory Bowel Disease (IBD), underscoring the polygenic nature and genetic interconnections of these conditions." (PMID 39219434, 2025).
lipoma (1 paper, 2025). A benign, usually painless, well-circumscribed lipomatous tumor composed of adipose tissue. "SETD5 expression was significantly higher in WDLPS than in lipomas (p = 0.01)." (PMID 41467459, 2025). "SETD5 expression was absent in normal adipose tissue and minimal in lipomas." (PMID 41467459, 2025).
liposarcoma (1 paper, 2025). A usually painless malignant tumor that arises from adipose tissue. "This study examined the immunohistochemical expression and prognostic significance of SETD5 in liposarcomas." (PMID 41467459, 2025). "Pleomorphic liposarcoma showed the highest SETD5 expression levels." (PMID 41467459, 2025). "SET domain containing 5 (SETD5), a chromatin regulator involved in adipocytic differentiation, has been identified in various cancers, but its immunohistochemical expression and prognostic significance in liposarcoma remain unclear." (PMID 41467459, 2025).
metastatic tumors (1 paper, 2017). "Genes that were up-regulated in primary and metastatic tumors included SETD5 (SET domain containing 5) and TFAP2A (transcription factor AP-2 alpha)." (PMID 28086829, 2017).
myeloid neoplasm (1 paper, 2023). Proliferation of myeloid cells originating from a primitive stem cell. "Other histone methylating genes, such as KMT5B/EZH1/KMT2D/KMT2E/SETD5, were also included in brown module, and related to pathological process or prognosis of myeloid neoplasms (MDS/AML)." (PMID 37953918, 2023).
pancreatic ductal adenocarcinoma (1 paper, 2022). An infiltrating adenocarcinoma that arises from the epithelial cells of the pancreas. "Although higher bulk H3 pan-Kac and H3K9ac and increased H3K9ac levels at target genes were observed in mESCs and murine PDAC (pancreatic ductal adenocarcinoma) cells upon Setd5 deficiency respectively." (PMID 34853439, 2022).
vascular malformation (1 paper, 2023). A non-neoplastic disorder that is the result of defects of vascular morphogenesis. "This includes some of the genes for moyamoya phenomenon, other vascular malformations, abnormalities of coagulation including CBL, DIAPH1, CHD4, CNOT3, and SETD5." (PMID 36253534, 2023).
viral infection (1 paper, 2021). "Notably, we detect DIUs for several of the same genes (Setd5, Arhgap12, Gpbp1, and Eri2), suggesting that hnRNP K’s role in viral infection is conserved between mice and humans and may, in part, be mediated by the same alternative splicing events." (PMID 34305890, 2021).
cancer (12 papers, 2013 to 2026). A tumor composed of atypical neoplastic, often pleomorphic cells that invade other tissues. "Aberrant SETD5 overexpression is associated with cancer progression in various cancer types, which is consistent with our findings." (PMID 37963940, 2023). "We hypothesized that SETD5 is involved in regulating CSC maintenance because CSCs are frequently a major cause of cancer recurrence and metastasis." (PMID 37963940, 2023). "SETD5 is frequently mutated and hyperactive in both human neurodevelopmental disorders and cancer, and could be down-regulated by degradation through the ubiquitin-proteasome pathway, but the biochemical mechanisms underlying such dysregulation are rarely understood." (PMID 36875494, 2023). "Another mechanism of SETD5 involvement in cancer is the regulation of cell cycle-related genes through activating the PI3K/AKT signaling pathway." (PMID 36875494, 2023). "SETD5 overexpression causes the upregulation of PI3K-AKT pathway-related genes and cancer stem cell (CSC) markers such as CD133, Kruppel-like factor 4 (KLF4), and estrogen-related receptor beta (ESRRB), leading to the gain of stem cell-like phenotypes." (PMID 37963940, 2023). "There is no clear evidence that OGT can be targeted for O-GlcNAcylation of RNA Pol II, resulting in transcriptional activation of CSC marker genes in SETD5-overexpressed cancer cells." (PMID 37963940, 2023). "Nevertheless, the evidence that the methylation of H3K36 plays an important role in regulating enhancer activity and SETD5 is amplified in many cancers suggests that SETD5 must play a pivotal role in many different cellular processes." (PMID 36875494, 2023). "SETD5 also promotes cancer stem-like properties in esophageal squamous cells and breast carcinomas." (PMID 37963940, 2023). "Epigenetic-based therapies are emerging as effective and valuable approaches in cancer, and targeting SETD5 may present a practical approach." (PMID 36875494, 2023). "Genomic alterations of SETD5 occur in multiple cancer types, implicating its cancer-promoting role." (PMID 36875494, 2023). "Further research on the discovery and use of SETD5 inhibitors to combat cancer subtypes could help maximize the effects of current therapeutic regimens." (PMID 36875494, 2023). "SETD5 is overexpressed and dysregulated in various types of cancer, including prostate cancer." (PMID 37963940, 2023). "Evidence for SETD5 functional relevance in cancer has recently accumulated." (PMID 37963940, 2023). "First, a deeper understanding of the enzyme’s intracellular effects and affected genes is needed since there is evidence that SETD5 may also act as a tumor driver in some stages of cancer development." (PMID 36875494, 2023). "SETD5 dysregulation has been linked to stem cell-like properties in some cancer types; however, the role of SETD5 in cancer cell stemness has not yet been determined." (PMID 37963940, 2023). "The identification of genes regulated by SETD5 in association with HDAC3 and PAF1 complexes has provided insight into physiology and pathology related to cancer or to neurodevelopmental disorders (NDDs), in which up- or downregulation of SETD5 expression has been detected, respectively." (PMID 36685966, 2022). "Besides, SETD5, a non-typical histone lysine methyltransferase linked to cancer stemness, predicts poor survival in NSCLC." (PMID 41601687, 2026). "Therefore, the findings support the hypothesis that aberrant SETD5 upregulation reactivates the transcription of stem cell marker genes via SETD5-mediated chromatin reprogramming, resulting in cancer cells gaining stemness." (PMID 37963940, 2023). "Therefore, SETD5 downregulation is linked to ID and ASD pathophysiology, whereas its upregulation may play a role in cancer development." (PMID 37963940, 2023).
cancer (continued). "However, aberrant overexpression of SETD5 may cause reactivation of stem cell marker genes via PAF1-mediated recruitment of RNA Pol II at their TSS, contributing to the stem cell-like phenotypes of cancer cells." (PMID 37963940, 2023).
tumor (9 papers, 2013 to 2023). "SETD5 contributed to tumor cell invasion and was associated with a poor prognosis in NSCLC patients." (PMID 37941780, 2023). "In terms of the mechanism, SETD5 is proposed to act as a tumor driver by inhibiting tumor suppressor gene transcription through H3K9 methylation via interacting with G9a/HDAC3 complex." (PMID 36875494, 2023). "A number of histone methyltransferases, including Setd3, Setd5, Suv39h2, Smyd3, Prmt3, Prmt6, Nsd1, and Nsd2, were up-regulated in metastases compared to disseminated tumor cells or primary tumors." (PMID 23520493, 2013). "SETD5 is an important methyltransferase that has been found to be abnormally expressed in multiple tumors, correlated with the patient prognosis, and involved in the regulation of tumor progression and metastasis." (PMID 37941780, 2023). "We performed clonogenic proliferation and tumorsphere formation assays to determine how SETD5 affected CRC cell self-renewal and tumor-initiating ability." (PMID 37963940, 2023). "Among these are the SET domain-containing 5 (Setd5) promoter 43, the Phosphoglucokinase (Pgk1) promoter 44, which are also from the PDGFB-driven tumor and normal comparison, displaying clear differences between the tumors." (PMID 37739938, 2023). "Similarly, our results indicated that SETD2, SETD5, and SETMAR were frequently deleted in ccRCC and they were located at 3p, implying their potential roles as tumor suppressors." (PMID 30755832, 2019). "Moreover, the Dox-inducible SETD5 overexpression-induced increase in cell survival rates and tumor-initiating ability was abolished in SETD5-depleted SW480 cells but not in control knockdown cells." (PMID 37963940, 2023). "Therefore, cell survival rates and sphere-forming ability were significantly lower in SETD5-depleted cells compared to control knockdown cells, implying that SETD5 may play a role in CRC self-renewal and tumor-initiating abilities." (PMID 37963940, 2023).
neurodevelopmental disorder (7 papers, 2022 to 2025). A behavioral and cognitive disorder with onset during the developmental period that involves impaired or aberrant development of intellectual, motor, or social functions. "In humans, heterozygous loss-of-function mutations in SETD5 cause a neurodevelopmental disorder termed IDD23 (also known as MRD23)." (PMID 41283518, 2025). "In this study, we revealed mitochondrial dysfunctions as possible contributors to the pathogenesis of neurodevelopmental disorders caused by mutations in the SETD5 gene." (PMID 37264456, 2023). "The de novo mutation of the SETD5 gene has been identified as a genetic cause of neurodevelopmental disorders, such as intellectual disability (ID), autism spectrum disorder (ASD), and KBG syndrome." (PMID 36875494, 2023). "SETD5 mutations were identified as the genetic causes of neurodevelopmental disorders." (PMID 34853439, 2022). "DNA methylation signature analysis in this patient revealed an episignature consistent with SETD5-related neurodevelopmental disorder and no other candidate variants were identified after screening the protein-coding regions of SETD5." (PMID 37745552, 2023). "SETD5 and SETD2 genes share functional similarities such as playing multiple roles in the central nervous system through histone and nonhistone methylation, and their dysfunction leads to complex neurodevelopmental disorders." (PMID 40642607, 2025).
adenocarcinoma (1 paper, 2023). A common cancer characterized by the presence of malignant glandular cells. "In addition, SETD5 and CD133 were found to be co-localized in adenocarcinoma tissue serial tissue." (PMID 37963940, 2023).
SETD5 also shares sentences with these, for which no sentence is quoted: Silver-Russell syndrome (2 papers); atypical lipomatous tumor (1); beta thalassaemia (1); cognitive deficit (1); colon cancer (1); dedifferentiated liposarcoma (1); endometrial carcinoma (1); Epileptic encephalopathy (1); gastric cancer (1); Hereditary breast cancer (1); hyperplastic polyp (1); leukemia (1); Macrocephaly (1); microphthalmia (1); myxoid liposarcoma (1); ovarian carcinoma (1); Overlap Syndrome (1); pleomorphic liposarcoma (1); prostate tumors (1); schizophrenia (1); Sotos syndrome (1); Timothy syndrome (1); Truncal obesity (1); well-differentiated liposarcoma (1).